DDAH2 (DDAH family member 2, ADMA-independent)
Diseases named in the same sentence as DDAH2 in open-access papers (continued):
Sharing a sentence is not in itself a finding about the gene and the disease.
Insulin resistance (2 papers, 2012 to 2025). Increased resistance towards insulin, that is, diminished effectiveness of insulin in reducing blood glucose levels. "Previous studies indicated higher level of ADMA causes insulin resistance and T2D, whereas higher expression of DDAH2 improves glucose-stimulated insulin secretion." (PMID 40864748, 2025). "Interestingly, we did not observe any association between the rs9267551 polymorphism in the DDAH2 gene and the HOMA index of hepatic insulin resistance (data not shown)." (PMID 22558392, 2012).
ischemia (2 papers, 2016 to 2019). A hypoperfusion of the BLOOD through an organ or tissue caused by a PATHOLOGIC CONSTRICTION or obstruction of its BLOOD VESSELS, or an absence of BLOOD CIRCULATION. "Furthermore, comparative studies performed in DDAH1+/−, DDAH2+/−, and DDAH2−/− mice have demonstrated the important role of DDAH2 in pathogenic retinal ischemia and ischemia-induced angiogenesis and the protective potential of DDAH2 inhibition against aberrant neovascularization." (PMID 31993367, 2019). "Deficiency of DDAH2 does not affect normal neuroretinal development or function but, in the context of ischemia, strongly promotes vascular regeneration and protects against pathological neovascularization." (PMID 27181226, 2016).
myocardial infarction (2 papers, 2019 to 2022). Gross necrosis of the myocardium, as a result of interruption of the blood supply to the area, as in coronary thrombosis. "In a study comprising 473 patients with acute myocardial infarction and 447 controls, the minor allele of DDAH2 rs805304 was significantly associated with a decreased risk of myocardial infarction." (PMID 35207213, 2022).
renal fibrosis (2 papers, 2020 to 2023). A final common manifestation of a wide variety of chronic kidney diseases characterized by glomerulosclerosis and tubulointerstitial fibrosis. "In contrast, nebivolol decreased the expression of PRMT1, ADMA, and DDAH2 and lessened renal fibrosis and capillary damage, and improved renal function; the exact mechanism is not known." (PMID 36817133, 2023). "To further determine the effect of renal ADMA on renal fibrosis, we injected nonsense control (NC), Ddah1 or Ddah2 siRNA to the UUO kidney through the left ureter." (PMID 32794631, 2020).
retinal ischemia (2 papers, 2016 to 2019). A ischemic disease that involves the retina. "eNOS-deficient mice exhibit a 46% reduction of the area of retinal ischemia and a reduction of retinal neovascularization by about 66% similar to our own findings in DDAH2-deficient mice." (PMID 27181226, 2016). "Here we show that in retinal ischemia, DDAH2 deficiency elevates ADMA, promotes retinal vascular regeneration and protects against aberrant neovascularization." (PMID 27181226, 2016). "Taken together this study suggests, that in retinal ischemia, DDAH2 deficiency elevates ADMA, promotes vascular regeneration and protects against aberrant angiogenesis." (PMID 27181226, 2016). "Therapeutic intervention to increase ADMA, for example by small molecules inhibition of DDAH2, may offer the means to promote vascular regeneration and prevent retinal neovascularization in common conditions associated with retinal ischemia." (PMID 27181226, 2016). "In summary, our results indicate that DDAH2 prevents ADMA upregulation in retinal ischemia, impairing retinal vascular regeneration and promoting aberrant neovascularization." (PMID 27181226, 2016). "To do this we investigated the expression of ADMA and L-NMMA in the ischemic murine retina and characterized DDAH1 and DDAH2 knockout mice in health and in an established model for retinal ischemia and neovascularization." (PMID 27181226, 2016). "To assess the role of DDAH2 on ADMA levels, retinal ischemia and neovascularization we investigated DDAH2 deficient mice in health and in the OIR mouse model." (PMID 27181226, 2016). "The aim of this study was to determine the roles of DDAH1, DDAH2, ADMA and L-NMMA in retinal ischemia-induced angiogenesis." (PMID 27181226, 2016). "To determine the effect of reduced DDAH1 and absent DDAH2 activity on retinal ischemia and neovascularization we investigated DDAH1+/− and DDAH2−/− deficient mice in two established models of ocular neovascularization." (PMID 27181226, 2016).
Shock (2 papers, 2006 to 2012). The state in which profound and widespread reduction of effective tissue perfusion leads first to reversible, and then if prolonged, to irreversible cellular injury. "The objectives of this study were to determine if functional polymorphisms in the DDAH2 gene were associated with plasma ADMA concentration, distinct hemodynamic states, and cardiovascular dysfunction in pediatric septic shock." (PMID 22428028, 2012). "In conclusion, we studied whether two known functional polymorphisms in the DDAH2 gene are associated with plasma ADMA concentration, distinct hemodynamic states, and cardiovascular dysfunction in pediatric septic shock." (PMID 22428028, 2012).
thymoma (2 papers, 2016 to 2019). A neoplasm arising from the epithelial cells of the thymus. "In pancreatic adenocarcinoma and thymoma DDAH1 and DDAH2 mRNA is significantly increased, whilst both DDAH1 and DDAH2 expression is decreased in lung squamous cell carcinoma." (PMID 31993367, 2019).
adenocarcinoma in situ (1 paper, 2016). A lesion in which the normally situated glands are partially or completely replaced by atypical cells with malignant characteristics. "DDAH2 was found to be expressed in fibroblasts of stroma of malignancies, with higher expression in minimally invasive adenocarcinoma (MIA) and invasive adenocarcinoma than in adenocarcinoma in situ (AIS)." (PMID 26515557, 2016).
age-related macular degeneration (1 paper, 2016). Age-related loss of vision in the central portion of the retina (macula), secondary to retinal degeneration. "To investigate the role of DDAH1 and DDAH2 in angiogenesis in choroidal neovascularization (CNV), a feature of age-related macular degeneration, we measured the extent of CNV induced by laser-rupture of Bruch’s membrane in heterozygous DDAH1 and homozygous DDAH2 deficient mice." (PMID 27181226, 2016).
allergic asthma (1 paper, 2014). A asthma with a basis in a pathological type I hypersensitivity reaction. "In summary, our data suggest that decreased expression of DDAH1 and DDAH2 in lungs may contribute to allergic asthma and overexpression of DDAH1 attenuates allergen-induced airway inflammation through modulation of Th2 responses." (PMID 24465497, 2014). "Our findings suggest that decreased expression of DDAH1 and DDAH2 in the lungs may contribute to allergic asthma and overexpression of DDAH1 attenuates allergen-induced airway inflammation through modulation of Th2 responses." (PMID 24465497, 2014).
asthma (1 paper, 2014). "Our data reveal that expression of DDAH1 and DDAH2 is decreased in the lungs in a mouse model of asthma, and overexpression of DDAH1 attenuates allergen-induced airway inflammation." (PMID 24465497, 2014). "We determined the expression of DDAH1 and DDAH2 in the lungs in a mouse model of asthma." (PMID 24465497, 2014). "DDAH1 and DDAH2 are responsible for metabolism of over 90% of ADMA in vivo, and our data support a role for DDAH downregulation in asthma pathogenesis." (PMID 24465497, 2014).
bacterial sepsis (1 paper, 2025). "This may not only lead to the passivation of NO signals but also result in the subsequent impairment of pathogen defense, indicating that DDAH2 promotes the response to severe bacterial sepsis to a large extent by regulating the inflammatory response of macrophages." (PMID 41050938, 2025).
chronic heart failure (1 paper, 2024). "MT ameliorated ISO-induced chronic heart failure by upregulating DDAH2 expression and suppressing cTnI, BNP, and ADMA expression." (PMID 39041001, 2024).
Cirrhosis (1 paper, 2014). A chronic disorder of the liver in which liver tissue becomes scarred and is partially replaced by regenerative nodules and fibrotic tissue resulting in loss of liver function. "In BDL-induced cirrhosis, it acts, instead, through DDAH-2, an enzyme responsible for the degradation of asymmetrical dimethylarginine (ADMA), an endogenous inhibitor of eNOS." (PMID 25174394, 2014).
cognitive decline (1 paper, 2022). "Progression of leukoaraiosis, a condition frequently met in neuropsychiatric disorders, relates to cognitive decline and thus could explain the link of DDAH2-cluster with cognition (learning and memory, cognition, synapse organization)." (PMID 36233204, 2022).
colonic tumors (1 paper, 2020). "However, our analysis of clinical samples showed the downregulation of DDAH1 and DDAH2 in colonic tumors." (PMID 32932854, 2020).
Crohn disease (1 paper, 2020). A gastrointestinal disorder characterized by chronic inflammation involving all layers of the intestinal wall, noncaseating granulomas affecting the intestinal wall and regional lymph nodes, and transmural fibrosis. "Supporting possible DDAHs involvement in predisposing to cancer development, colonic DDAH1 expression has been upregulated in patients with Crohn’s disease, solely during the disease flare, while that of DDAH2 was also upregulated during remission." (PMID 32932854, 2020).
diabetic cardiomyopathy (1 paper, 2020). Diabetic cardiomyopathy is a disorder of the heart muscle in people with diabetes. "The DDAHs association with FGF2 warrants further investigation as well, as DDAH2 has recently been shown to alleviate fibrosis associated with diabetic cardiomyopathy and DDAH1 to inhibit the Wnt/β-catenin pathway, EMT, and gastric cancer cell migration." (PMID 32121248, 2020).
haemorrhagic stroke (1 paper, 2020). "Genetic alterations in DDAH2 are linked to haemorrhagic stroke, as has been observed in independent case-control studies." (PMID 33447134, 2020).
Hypercholesterolemia (1 paper, 2025). An increased concentration of cholesterol in the blood. "Research indicates that DDAH consists of two subunits, DDAH1 and DDAH2, which are associated with cardiovascular diseases induced by hypercholesterolemia, hypertension, abdominal obesity, and diabetes mellitus." (PMID 40149398, 2025).
leukoaraiosis (1 paper, 2022). "Lastly, the G allele of DDAH2 (−449 G/C) was positively associated with leukoaraiosis and high ADMA levels." (PMID 36233204, 2022).
mental disorder (1 paper, 2022). A disease that has its basis in the disruption of mental process. "Despite all these limitations, the present work provides preliminary evidence that DDAH1 and DDAH2 are co-regulated with genes involved in mental disorder development and derangement." (PMID 36233204, 2022).
Myocardial fibrosis (1 paper, 2025). "The overexpression of DDAH2 improves myocardial fibrosis and cardiac function by activating the DDAH/ADMA/eNOS/NO pathway, thereby delaying the progression of DCM." (PMID 40723788, 2025).
Obesity (1 paper, 2022). Accumulation of substantial excess body fat. "Another study of DNA methylation in whole blood and the association with obesity observed the association between DNA methylation changes of Ddah2, Cux1, Notch4, and Dst with BMI." (PMID 35458198, 2022).
rheumatoid arthritis (1 paper, 2021). A chronic, systemic autoimmune disorder characterized by inflammation in the synovial membranes and articular surfaces. "Among these novel identified genes, several genes (e.g., LY6G5B and DDAH2) were associated with autoimmune-related diseases, including rheumatoid arthritis and type 1 diabetes." (PMID 34872583, 2021).
Right ventricular hypertrophy (1 paper, 2020). In this case the right ventricle is more muscular than normal, causing a characteristic boot-shaped (coeur-en-sabot) appearance as seen on anterior- posterior chest x-rays. "Downregulation of DDAH1 expression and activity may be involved in this; however, knockout of the Ddah1 gene does not modify the hypoxia-induced pathophysiological changes of pulmonary blood pressure and right ventricular hypertrophy, possibly due to compensatory upregulation of DDAH2 protein." (PMID 33281630, 2020). "We measured ADMA concentration in plasma and lungs, DDAH1 and DDAH2 mRNA and protein expression in the lungs, right ventricular systolic pressure (RVSP), right ventricular hypertrophy by the Fulton index, and cardiomyocyte hypertrophy by dystrophin staining of the heart." (PMID 33281630, 2020).
ulcerative colitis (1 paper, 2020). An inflammatory bowel disease involving the mucosal surface of the large intestine and rectum. "In patients with ulcerative colitis, only DDAH2 has been upregulated, and exclusively during the disease flare." (PMID 32932854, 2020).
Ureteral obstruction (1 paper, 2020). Obstruction of the flow of urine through the ureter. "Normal saline, ADMA, nonsense control siRNA, Ddah1 siRNA or Ddah2 siRNA was administered into the kidney through the left ureter in a mouse model of unilateral ureteral obstruction (UUO)." (PMID 32794631, 2020). "Knockdown of Ddah1 or Ddah2 in unilateral ureteral obstruction kidneys increased the amount of ADMA and inhibited the expression of fibrotic proteins." (PMID 32794631, 2020).
cancer (7 papers, 2010 to 2024). A tumor composed of atypical neoplastic, often pleomorphic cells that invade other tissues. "Hyper-methylated genes included previously reported targets of recurrent hyper-methylation in OSCC, such as DDAH2, CCNA1, DCC, as well as some cancer-associated genes including HRAS." (PMID 38589501, 2024). "Still, in line with the cancer-promoting activities attributed to DDAH1 and DDAH2, the expression ratio (tumor-to-adjacent) of DDAH2 tended to increase with cancer advancement, reflecting lymph node involvement." (PMID 32932854, 2020). "The range of cancer types that display altered DDAH1 expression is significantly broader than that for DDAH2." (PMID 31993367, 2019). "The expression of DDAH2 and systemic SDMA and DMA were, in turn, associated with circulating SCGFβ, a growth factor for primitive hematopoietic progenitor cells, which is overexpressed in cancer by circulating cancer cells and drug-resistant cancer stem cells." (PMID 32872669, 2020). "DDAH1 and DDAH2 expression in human cancer tissues and cell lines." (PMID 31993367, 2019). "The DDAH2 status, as well as the precise role of either isoform in cancer, remains largely unknown." (PMID 32872669, 2020). "Despite enhanced DDAH2 expression being linked to a handful of cancers such as lung and prostate, the lack of a robust and reproducible in vitro DDAH2 activity assay represents a significant limitation for the development and pharmacokinetic characterization of DDAH2 activity modulators." (PMID 31993367, 2019). "The DDAH2 expression tended to be less decreased in N1/N2 than N0 cancers (by 1.5-fold, p = 0.059) and stage III/IV than 0/I/II cancers (by 1.5-fold, p = 0.058)." (PMID 32932854, 2020). "In addition, the local expression of key pathway enzymes (ARG1, ARG2, DDAH1, DDAH2, NOS2, ODC1, PRMT1, and PRMT5), as potential therapeutic targets, was evaluated in reference to cancer pathology." (PMID 32872669, 2020). "Although not yet known, this regulation of DDAH2 by estradiol and ER may play an important role in cancers driven by excessive ER signaling, such as those of the breast." (PMID 31993367, 2019). "DDAH2 diffusely stained cancer stroma, but the expressing cells could not be identified." (PMID 26515557, 2016). "Interestingly, with the exception of these three cancers, the expression of DDAH1 and DDAH2 does not change in the same direction." (PMID 31993367, 2019).
tumor (7 papers, 2010 to 2023). "On the contrary, DDAH1 in tumors exhibited a negative correlation with another angiogenic factor, FGF2, and DDAH2 in tumor-adjacent tissue—a positive association with an angiostatic IP-10." (PMID 32872669, 2020). "The DDAH2 gene showed more differential methylation (hypermethylation) in tumor tissue in BRAF wild-type tumors compared to the mutant group." (PMID 36975440, 2023). "Compared to normal mucosa, ARG1, PRMT1, and PRMT5 were overexpressed in both tumor and tumor-adjacent tissue and DDAH2 solely in tumor-adjacent tissue." (PMID 32932854, 2020). "Expression of tumor fibroblast-derived DDAH2 in vascular endothelium led to an increase of NO production, followed by increased vascular endothelial cell proliferation and migration." (PMID 26515557, 2016). "Whilst together these findings may be indicative of a model whereby DDAH2 promotes tumor angiogenesis, a more definitive assessment of the role of DDAH2 in vivo is clearly required." (PMID 31993367, 2019). "DDAH2 may act not only on vascular endothelial cells by releasing them from ADMA-induced eNOS inhibition but also on tumor cells by stimulating their expression of VEGF." (PMID 26515557, 2016). "Two additional, arbitrarily chosen loci that showed age-related hypermethylation on the array, DDAH2, an epigenetic marker associated with cellular differentiation, and TET2, a putative tumor suppressor gene, also were substantially hypermethylated in old epidermis samples." (PMID 20523906, 2010). "Tumor-adjacent tissue had higher expression of ARG1, DDAH1, and DDAH2 and lower NOS2 than patients-matched tumors." (PMID 32932854, 2020). "Only the fold change in DDAH2, ODC1, and PRMT5 expression differed significantly with overall TNM stage, with tumor-to-adjacent ratio decreasing in a stepwise manner along with increasing stage." (PMID 32872669, 2020). "In contrast to DDAH1, the importance of DDAH2 in ADMA metabolism and thus tumor angiogenesis is still unclear." (PMID 31993367, 2019). "Pairwise analysis showed significantly downregulated expression of ARG1 (by 2.2-fold, p = 0.025), DDAH1 (by 1.4-fold, p = 0.016), and DDAH2 (by 1.6-fold, p = 0.005) and upregulated expression of NOS2 (by 2.6-fold, p = 0.003) in tumor as compared to adjacent, macroscopically normal tissue." (PMID 32932854, 2020). "The expression of DDAH2 was significantly elevated, and that of DDAH1 non-significantly higher, exclusively in non-cancerous tumor-adjacent tissue." (PMID 32932854, 2020).
infection (2 papers, 2011 to 2012). The state of being infected such as from the introduction of a foreign agent such as serum, vaccine, antigenic substance or organism. "Only DDAH-2 isoform appeared to be up-regulated at the transcriptional level throughout the infection process." (PMID 21408057, 2011). "DDAH-1 and, to a lesser extent, DDAH-2 immunoreactivities were observed in several brain areas (cortex, hippocampus, amygdala) and notably in the hypothalamic and thalamic groups of nuclei in healthy and infected rat (at D10 and D16 post-infection) groups." (PMID 21408057, 2011).